CASZ1 (castor zinc finger 1)
Description:
Transcriptional activator. Involved in vascular assembly and morphogenesis through direct transcriptional regulation of EGFL7.
Synonyms: CST; SRG; ZNF693; FLJ20321; castor; CAS11; dJ734G22.1
Tractability: PROTAC: UniProt records ubiquitination sites on it; ubiquitination databases record sites on it.
Gene: Protein-coding gene on chromosome 1 (10,636,604 to 10,796,650, reverse strand). Ensembl gene ENSG00000130940.
Subcellular location: Nucleus
Subcellular location (Human Protein Atlas): Nucleoplasm; Cytosol; Vesicles
Gene Ontology:
Molecular function: DNA-binding transcription activator activity, RNA polymerase II-specific; RNA polymerase II transcription regulatory region sequence-specific DNA binding; DNA-binding transcription factor activity, RNA polymerase II-specific
Biological process: positive regulation of DNA-templated transcription; positive regulation of transcription by RNA polymerase II; regulation of neuron differentiation; regulation of DNA-templated transcription
Cellular component: chromatin; nucleoplasm; nucleus
Genetic constraint (gnomAD): Loss-of-function variants: 26 observed, 126.47 expected, observed/expected ratio (o/e) 0.21, 90% interval 0.15 to 0.28. The upper end of that interval is the gene's LOEUF score, 0.28, which puts it in group 1 of 6, group 1 being the genes least tolerant of losing a copy. Missense variants: 2,080 observed, 2,349.9 expected, observed/expected ratio (o/e) 0.89, 90% interval 0.85 to 0.92. Synonymous variants: 1,029 observed, 1,029 expected, observed/expected ratio (o/e) 1, 90% interval 0.95 to 1.05.
Gene-disease validity (ClinGen):
ClinGen rates the evidence that CASZ1 causes each of these diseases.
congenital heart disease (autosomal dominant): Limited. A heart disease that is present at birth.
Homologues: Orthologues: macaque CASZ1 (98% identical), rat Casz1 (91% identical), guinea pig CASZ1 (91% identical), dog CASZ1 (90% identical), chimpanzee CASZ1 (89% identical), pig CASZ1 (84% identical), tropical clawed frog casz1 (70% identical), zebrafish casz1 (62% identical), rabbit CASZ1 (61% identical), Drosophila melanogaster cas (13% identical).
Diseases named in the same sentence as CASZ1 in open-access papers:
CASZ1 is named in the same sentence as 83 diseases in open-access papers, as found by Europe PMC text mining. Sharing a sentence is not in itself a finding about the gene and the disease. The quoted sentences say what the papers report.
neuroblastoma (29 papers, 2011 to 2025). Neuroblastoma (NB) is the most common solid, extracranial childhood tumor. "For instance, CASZ1 regulates the expression of genes associated with cell growth and development while inhibiting cell migration and tumorigenicity in neuroblastoma cell lines." (PMID 40723577, 2025). "The deletion or inactivation of CASZ1 mutations can lead to human developmental diseases or tumors, including congenital heart disease, cardiovascular disease, and neuroblastoma." (PMID 38053207, 2023). "This proposes another pathogenic mechanism: CASZ1 downregulation predisposes neuroblastoma, which in turn leads to hypertension." (PMID 37509718, 2023). "CASZ1 encodes a zinc finger transcription factor whose dysregulated expression was linked to the pathobiology of neuroblastoma, glioma, and hepatocellular carcinoma, and aberrant fusion transcripts of CASZ1 were reported in colorectal and bladder cancers." (PMID 37300660, 2023). "In this study, we performed loss and gain of function studies of CASZ1 in neuroblastoma cell lines paired with detailed epigenetic and transcriptomic characterization." (PMID 36243768, 2022). "We next focused on 1p-intact neuroblastomas and studied the mutational spectrum of neuroblastoma candidate genes (particularly chromosome 1 genes CASZ1, CHD5, PTPN14, KIF1Bβ, NTRK1, and TP73), and their association with clinical prognostic variables." (PMID 35768791, 2022). "Allelic loss of CASZ1 and epigenetic suppression of the remaining allele has been implicated in neuroblastoma tumorigenesis." (PMID 32060262, 2020). "CASZ1 acts as a tumor suppressor gene, and researchers have shown that CASZ1 is downregulated in high-risk phenotypes of neuroblastoma." (PMID 26943042, 2016). "Consistently, we find low CASZ1a or CASZ1b are associated with poor prognosis of neuroblastoma patients, which is similar to what we find for total CASZ1." (PMID 21490919, 2011). "Moreover, MEKi treatment of a KRAS mutated neuroblastoma cell line NBEB (KRAS_G12D) also increased CASZ1 expression." (PMID 32060262, 2020). "However the resolution of our assays with FFPE samples allowed us to map a 1p36.22 breakpoint created by a single copy loss to the CASZ1 locus, a zinc finger gene implicated in neuroblastoma." (PMID 23226320, 2012). "We recently demonstrated that low total CASZ1 expression is associated with poor prognosis in neuroblastoma patients and the full length isoform CASZ1a suppresses neuroblastoma growth in vitro and in vivo, however it is important and necessary to assess the function of CASZ1b." (PMID 21490919, 2011). "Additionally, loss of CASZ1 is associated with poor prognosis in neuroblastomas." (PMID 31481981, 2019). "Studies on the expression profiles of CASZ1 in a variety of solid tumors have revealed low expression in neuroblastoma and hepatocellular carcinoma and high expression in malignancies such as epithelial ovarian cancer." (PMID 39235847, 2024). "Given that neuroblastoma is derived from neural crest cells or sympathoadrenal precursors, these results collectively suggest that CASZ1 probably promotes cell differentiations in sympathoadrenal lineage." (PMID 37509718, 2023). "In conclusion, as a tumor suppressor gene of neuroblastoma, CASZ1 is involved in the progression of NB through cell cycle regulation and is associated with poor prognosis." (PMID 38053207, 2023). "Second, CASZ1 was prominently known for its tumor suppression role in neuroblastoma and other cancers." (PMID 36069056, 2023). "The downregulation of CASZ1 in neuroblastoma is not only attributed to the genetic anomaly (1p36 LOH), but also epigenetic modifications." (PMID 37509718, 2023). "For example, CASZ1 suppresses NB partially due to upregulation of NGFR, which encodes a Fas/TNF-R family receptor that mediates apoptosis of neuroblastoma cells in the presence of nerve growth factor (NGF)." (PMID 37509718, 2023).
neuroblastoma (continued). "The results demonstrate that CASZ1 can regulate gene expression to act as a tumor suppressor in neuroblastoma tumors." (PMID 36344988, 2022). "The downregulated CASZ1 exert tumor‐suppressive functions via regulating oncogenes in neuroblastoma and hepatocellular cancer." (PMID 36276925, 2022). "Castor zinc finger 1 (CASZ1) is a transcription factor, prominently known for its tumor suppression role in neuroblastoma and other cancers." (PMID 31481981, 2019). "In another study, the overexpression of EZH2 in neuroblastoma was found to be associated with poor patient prognosis, and PRC2 mediated the silencing of tumor suppressor genes like CASZ1 through epigenetic changes." (PMID 31920530, 2019). "CASZ1 regulates tumor growth and the process of development and thus can be a candidate for tumor suppression in neuroblastomas." (PMID 31481981, 2019). "Casz1 is also a tumor-suppressor gene mapping to chromosome 1p36.22 in humans, which is deleted in neuroblastoma and other cancers." (PMID 29467767, 2018). "CASZ1 is associated with the RP11-164P12.4 mRNA (PCC = 0.924 in MM vs. PM), which has been shown to suppress neuroblastoma cell growth in vitro and in vivo." (PMID 28225791, 2017). "Both CASZ1 and NuRD subunit CHD5 have been identified as chromosome 1p36 tumor suppressor genes in neuroblastoma, and both are frequently lost in high-risk neuroblastoma patients." (PMID 26296975, 2015). "In clinical primary tumor sumples, the expression of CASZ1 is significantly decreased in aggressive neuroblastoma compared with the favorable tumors." (PMID 22928040, 2012). "In humans, the CASZ1 gene localizes to chromosome 1p36, and deletion of this region frequently occurs in cancers such as neuroblastoma, melanoma, oligodendroglioma and breast cancers." (PMID 21490919, 2011). "Recently we have shown that full length CASZ1 (CASZ1a isoform) functions as a neuroblastoma tumor suppressor, however a functional role for the CASZ1b has not been described to date." (PMID 21490919, 2011). "Moreover, CASZ1’s involvement in tumor progression has been reported, with implications for neuroblastoma and hepatocellular carcinoma." (PMID 39235847, 2024). "Taken together, CASZ1 acts as a multidirectional suppressor in neuroblastoma." (PMID 37509718, 2023). "However, CASZ1 is suppressive to neuroblastoma, and is frequently downregulated in neuroblastoma cell lines and clinical samples." (PMID 37509718, 2023). "Similarly in neuroblastoma cell lines, the CASZ1 mRNA level increases concomitantly when neuroblastoma cells are induced to differentiate." (PMID 37509718, 2023). "Although overall mutational frequencies in neuroblastoma are low, CASZ1 has not been previously noted to be associated with other gene mutations in neuroblastoma." (PMID 35768791, 2022). "With regard to NGFR, the present study provides evidence that one mechanism by which VPA upregulates p75NTR expression involves the depletion of the PRC2 core component EZH2 and the consequent derepression of CASZ1, a neuroblastoma tumour suppressor and a positive regulator of NGFR." (PMID 32712736, 2020). "CASZ1 is downregulated and functions as a crucial tumor suppressor in neuroblastoma." (PMID 29506567, 2018). "The loss of heterozygosity and/or EZH2-mediated H3K27me3 modification can silence the CASZ1 gene in tumor samples from patients with a poor prognosis of neuroblastoma (NB)." (PMID 38053207, 2023). "Treatment of neuroblastoma cell lines with EZH2 antagonists, such as valproic acids or DZNep, can restore CASZ1 expression, inhibiting tumor cell proliferation and promoting morphological differentiation." (PMID 37509718, 2023). "CASZ1 suppresses CRC transcription factor expression by reducing H3K27ac signals and enhancer activities on their gene loci, thereby inhibiting neuroblastoma oncogenesis." (PMID 37509718, 2023). "In neuroblastoma and HCC, CASZ1 expression was lower in aggressive stage tumors or in cases with poor prognosis." (PMID 31481981, 2019).
neuroblastoma (continued). "Interestingly, the epigenetically silenced neuroblastoma tumor suppressor gene CLU was induced in both cell lines, together with another tumor suppressor CASZ1 only in IMR32 cells." (PMID 32210188, 2020). "It has been reported that high EZH2 expression is prognostic for poor clinical outcome in neuroblastoma patients and that EZH2-catalyzed H3K27me3 is responsible for transcriptional repression of several neuroblastoma tumor-suppressor genes, including CASZ1 GLU, RUNX3, and NGFR19." (PMID 30631055, 2019). "Casz1 has been shown to interact with histones and recruit nucleosome remodeling and histone deacetylase complex, and Polycomb complex histone methytransferase subunits EZH2 to regulate gene transcription in HEK293T and neuroblastoma cells." (PMID 29467767, 2018). "Expression of the neuroblastoma tumor suppressor gene CASZ1 was also notably absent in P896-FB, in contrast to the NMC lines." (PMID 29348827, 2017). "However, a large number of genes located within the 1p36 region have been proposed as tumor suppressors in neuroblastoma and other tumors, including CHD5, CAMTA1, miRNA-34a, CASZ1, KIF1B, and the HES gene family." (PMID 27014418, 2016). "We would like to thank the ROCKLAND Immunochemicals for Research Company for helping us produce the anti-CASZ1 antibody; thank the Children's Oncology Group (COG) neuroblastoma Biology Group Committee for providing us with total RNA from neuroblastoma tumors from patients prior to chemotherapy." (PMID 21490919, 2011).
Hypertension (13 papers, 2016 to 2025). The presence of chronic increased pressure in the systemic arterial system. "Two genome-wide association studies (GWASs) have revealed a genetic association between the human Casz1 locus and hypertension, suggesting a potential link between CASZ1 and cardiovascular dysfunction." (PMID 38053207, 2023). "GWAS on hypertension have reported that three single-nucleotide polymorphisms (SNPs) in the CASZ1 gene, rs880315, rs284277 and rs12046278, are associated with hypertension." (PMID 38053207, 2023). "Multiple GWAS (Genome-wide association studies) studies involving Europeans or Asians have discovered various CASZ1 risk alleles, which probably cause CASZ1 misexpression linked to hypertension, although the mechanisms are still unclear." (PMID 37509718, 2023). "Particularly, SNP rs284277C is a risk allele for primary aldosteronism (PA), a hypertensive disease mostly caused by aldosterone producing adenoma, where CASZ1 aberrant upregulation was observed." (PMID 37509718, 2023). "SNP rs880315 in CASZ1 (Zinc Finger Protein Castor Homolog 1) nominally associated with hypertension (DBP≥90 mmHg) in the mid-tier age group (≥30 to <60 years), but not in younger (<30 years) or older individuals (≥60 years)." (PMID 34793544, 2021). "Casz1 is critical for the development of vasculature and differentiation of cardiomyocytes in Xenopus and mice, and human CASZ1 locus has been linked to high blood pressure by genome-wide association studies." (PMID 29467767, 2018). "In addition, we identified three SNPs in two novel genes (LOC729251 and TCEANC) and seven SNPs in five previously reported genes (FGF5, ATP2B1, CYP17A1, MTHFR and CASZ1) nominally associated with hypertension (Pmeta < 0.05)." (PMID 27480026, 2016). "However, more studies are necessary to verify the role of CASZ1 in these reported tumor types, and whether CASZ1 mutations/SNPs are sufficient to cause hypertension and CVD also requires further elucidation." (PMID 37509718, 2023). "For instance, castor zinc finger 1 (CASZ1) not only correlates with AF but also with the incidence of hypertension." (PMID 38920645, 2024). "Genetic and epigenetic alternations of CASZ1 have been characterized in multiple cardiovascular disorders, such as congenital heart diseases, chronic venous diseases, and hypertension." (PMID 37509718, 2023). "A variety of statistically significant genetic polymorphisms were identified that can be attributed to the heritability of varicose veins affecting inflammation and immunity (eg, PPP3R1, EBF1, and GATA2), hypertension (eg, CASZ1), and vascular architecture (eg, CASZ1, PIEZO1, and STIM2)." (PMID 41391741, 2025). "Improper regulation of CASZ1 could potentially lead to the defects that are collectively observed in DS, such as cognitive defects, congenital heart defects, and hypertension." (PMID 31801612, 2019). "The discovery that CASZ1 and RXFP2 are involved in the development of PA provides new pathophysiological insight and opens perspectives for the diagnosis and treatment of arterial hypertension." (PMID 36057693, 2022). "Still, restricting the GRS to one single SNP per gene (rs17035646 for CASZ1 and rs77270397 for EEF1DP3, FRY-AS1) led to similar findings, i.e., the lack of association between the short GRS and hypertension control." (PMID 37479854, 2023). "Therefore, there might not exist a simple connection between CASZ1 levels and hypertension." (PMID 37509718, 2023).
hepatocellular carcinoma (9 papers, 2018 to 2025). A malignant tumor that arises from hepatocytes. "Low expression of CASZ1 in hepatocellular carcinoma, colorectal cancer, esophageal cancer, lung adenocarcinoma and clear cell renal cell carcinoma is associated with poor prognosis, while high expression of CASZ1 in glioma, EOC and lung cancer promotes cancer progression." (PMID 38053207, 2023). "We provide evidence that miR-541-3p concurrently reduces apoB and increases apoA1 in human hepatoma cells by regulating 2 different TFs, Casz1 and Znf101." (PMID 39782688, 2025). "The tumor suppressive effects of CASZ1 are also evident in rhabdomyosarcoma and hepatocellular carcinoma." (PMID 37509718, 2023). "Conversely, CASZ1 is downregulated in hepatocellular carcinoma, colorectal cancer, esophageal cancer, lung adenocarcinoma, and clear cell renal cell carcinoma, and its decreased expression is linked to patient prognosis, with this diminished expression serving as a potential prognostic indicator." (PMID 38053207, 2023). "However, the prognostic importance and biologic functions of CASZ1 in hepatocellular carcinoma (HCC) are still unclear." (PMID 29506567, 2018). "Furthermore, CASZ1 has been identified as a tumor suppressor in hepatocellular carcinoma, and it has been proposed that CASZ1 may serve as a potential driver or biomarker for certain skin diseases." (PMID 40723577, 2025). "CASZ1 downregulation was correlated with aggressiveness and poor outcome in hepatocellular carcinoma (HCC)." (PMID 31481981, 2019). "In hepatocellular carcinoma (HCC) samples, CASZ1 is downregulated compared to normal tissues and mainly localizes in the cytoplasm." (PMID 37509718, 2023).